ABL1 (ABL proto-oncogene 1, non-receptor tyrosine kinase)
Diseases named in the same sentence as ABL1 in open-access papers (continued):
Sharing a sentence is not in itself a finding about the gene and the disease.
bladder cancer (11 papers, 2019 to 2025). "More precisely, ABL1 is a protein-tyrosine kinase expressed in numerous neoplasias, and it has been detected in urine specimens of patients with bladder carcinoma, linked to the increased number of urothelial cells observed in these patients." (PMID 37569864, 2023). "It has also been reported that the LOH of ABL1 can be used as a diagnostic marker for bladder cancer recurrence." (PMID 33952249, 2021). "And it has been reported that about 2.2% of mutations in the ABL1 are found, especially in bladder cancer patients." (PMID 33952249, 2021). "In particular, an association with bladder cancer in the BCR region of ABL1 has also been reported." (PMID 33952249, 2021). "In addition, the ABL1 region at position 9q34.12 on chromosome 9 has also been reported as a loss of heterozygosity (LOH) marker that may affect the recurrence of bladder cancer." (PMID 33952249, 2021). "Therefore, it is suggested that the ABL1-MS1 region may affect the regulation of ABL1 expression in bladder cancer, and the identification of rare alleles of the ABL1-MS1 may suggest predictability as a susceptibility marker for bladder cancer." (PMID 33952249, 2021). "The XPERT© Bladder Cancer Monitor is a test for detecting the five mRNA sequences (ABL1, CRH, IGF2, UPK1B, ANXA10) in urine." (PMID 35804953, 2022). "It is known that the expression of ABL1 is high in solid cancers including bladder cancer, and the structural characteristics of ABL1 are related to the expression." (PMID 33952249, 2021). "Based on the detection of five mRNA targets in urine (CRH, IGF2, UPK1B, ANXA10, and ABL1), Xpert Bladder Cancer (Xpert BC) is a recently developed detector for the detection of bladder cancer, which is non-invasive and highly economical." (PMID 33563292, 2021). "In addition, since abnormal expression of ABL1 has been reported in solid cancers including bladder cancer, the effect of this VNTR region on the expression of ABL1 was investigated." (PMID 33952249, 2021). "Therefore, the ABL1-MS1 region can affect ABL1 expression of bladder cancer." (PMID 33952249, 2021). "Data identified that in the low HER2 cohort and different ATM levels (high/low); ABL1, SMAD4, RB1 and PARP1 were significantly upregulated and AKT1, AKT2, TSC2, RPTOR and mTOR were significantly downregulated in bladder cancer." (PMID 36056635, 2022). "Investigating the level of transcription of the reporter gene driven by the ABL1 promoter, VNTR showed inhibition of ABL1 expression in non-cancer cells 293 T, but not in bladder cancer cells." (PMID 33952249, 2021). "Although there were reports of structural features in the BCR region of ABL1, VNTR was not reported in previous studies, so this study focused on the association between VNTR in the BCR region and bladder cancer." (PMID 33952249, 2021). "We also examined the transcription level of the reporter gene driven by the ABL1 promoter to determine if the VNTR region influenced gene expression, and that VNTR showed inhibition of ABL1 expression in non-cancer cells 293 T, but not in bladder cancer cells." (PMID 33952249, 2021).
chronic eosinophilic leukemia (11 papers, 2013 to 2024). "Many of these breakpoints corresponded to known gene fusions, including BCR/ABL1 in CML, FIP1L1/PDGFRA in eosinophilic leukemia, and NPM1/ALK in anaplastic large cell lymphoma (ALCL)." (PMID 23637631, 2013).
ovarian carcinoma (11 papers, 2009 to 2025). A malignant neoplasm originating from the surface ovarian epithelium. "In ovarian cancer, overexpression of ABL1 has been linked to poor patient outcomes, and ABL1 plays a role in the early stages of the DDR, regulating key processes such as cell cycle progression and DNA repair." (PMID 40918650, 2025). "This study used a two-stage approach to assess the contribution of inherited variation in 39 cell cycle genes to the risk of epithelial ovarian cancer and found some evidence of association at ABL1 rs2855192." (PMID 19738611, 2009). "In the discovery set, SNPs in several genes were found to be associated with the risk of ovarian cancer; of these, five genes (ABL1, CCND3, CDKN1A, E2F3 and CDK2) were significant in log-additive models (P-value <0.05)." (PMID 19738611, 2009). "Nucleotide polymorphism in the ABL1 gene has been associated with risk of ovarian cancer." (PMID 24001041, 2013). "Association between risk of ovarian cancer and ABL1 rs2855192 found in the original population [odds ratio, ORBB vs AA 2.81 (1.29–6.09), P=0.01] was also observed in a replication population, and the association remained suggestive in the combined analysis [ORBB vs AA 1.59 (1.08–2.34), P=0.02]." (PMID 19738611, 2009). "We demonstrate that tyrosine kinase ABL1 inhibitors inhibit cancer cell proliferation more efficiently in ovarian cancer cell lines with SYCP2 overexpression." (PMID 40918650, 2025). "Our investigation further suggests that ovarian cancer cells with elevated SYCP2 expression are highly sensitive to ABL1 inhibitors, such as imatinib and dasatinib, which impair this pathway." (PMID 40918650, 2025). "While our findings suggest that SYCP2-mediated TC-HR operates independently of RAD52 in ovarian cancer, the potential cooperation between these ABL1 substrates—especially under stress conditions—merits further investigation." (PMID 40918650, 2025). "In this study, we discovered a novel function of ABL1 kinase in ovarian cancer, where it phosphorylates the overexpressed SYCP2." (PMID 40918650, 2025). "Our study underscores the potential of targeting meiotic recombination proteins, like SYCP2, and the unexplored function of ABL1 at R-loops, as novel therapeutic strategies in overcoming drug resistance and improving outcomes for patients with ovarian cancer." (PMID 40918650, 2025). "Here, we treated ovarian cancer cell lines exhibiting varying mRNA levels of SYCP2 with three FDA-approved TKIs targeting ABL1—dasatinib, nilotinib, and imatinib." (PMID 40918650, 2025). "Overall, these findings highlight a novel therapeutic mechanism where ABL1 inhibitors induce cell death in platinum-resistant ovarian cancer by impairing transcription-coupled homologous recombination repair." (PMID 40918650, 2025). "However, the function of ABL1 within the TC-HR pathway remains largely unexplored, presenting an opportunity to investigate its involvement in ovarian cancer to uncover new therapeutic vulnerabilities." (PMID 40918650, 2025). "This discovery of SYCP2’s mechanism in DDR provides novel insight that TKIs can impair transcription-associated homologous recombination repair through ABL1-mediated SYCP2 phosphorylation, thus a potential inhibitory effect on platinum-resistant ovarian cancer cells." (PMID 40918650, 2025). "As such, our findings expand the application of targeting ABL1 for other cancer types and could be an option when formulating drug combinations for platinum-resistant ovarian cancer." (PMID 40918650, 2025). "Although ABL1 is ubiquitously expressed across cell types, studies including TCGA data indicate that in certain ovarian cancer subtypes—particularly epithelial ovarian carcinomas with poor prognosis—ABL1 expression and kinase activity may be elevated." (PMID 40918650, 2025).
ovarian carcinoma (continued). "Building upon our previous findings that SYCP2 promotes homologous recombination (HR) by stimulating R-loop formation at sites of DNA damage, we sought to understand the observed correlation between SYCP2 expression levels and sensitivity to ABL1 inhibitors in ovarian cancer cells." (PMID 40918650, 2025). "We found that ABL1 inhibitors, such as imatinib and dasatinib, exhibited a negative correlation with platinum resistance, suggesting they could serve as potential treatment options for ovarian cancer cells with overexpressed SYCP2." (PMID 40918650, 2025). "To evaluate the inhibitory effects of ABL1 inhibitors on ovarian cancer cells with elevated SYCP2 expression, we measured expression of SYCP2 in several ovarian cancer cell lines." (PMID 40918650, 2025). "Moreover, ABL1-mediated Y739 phosphorylation of SYCP2 promotes function of SYCP2 at sites of R-loops by facilitating RAD51 localization and repair, contributing to ovarian cancer cell survival." (PMID 40918650, 2025).
triple-negative breast carcinoma (10 papers, 2014 to 2026). An invasive breast carcinoma which is negative for expression of estrogen receptor (ER), progesterone receptor (PR), and human epidermal growth factor receptor 2 (HER2). "Using an intracardiac mouse model of metastasis, shRNA-mediated knockdown of both ABL1 and ABL2 in bone tropic triple-negative breast cancer cells decreased metastasis to the bone and increased overall survival." (PMID 34022881, 2021).
gastric cancer (9 papers, 2012 to 2023). A primary or metastatic malignant neoplasm involving the stomach. "The expression of gastric cancer gene abl1 was significantly higher in infection-III than in infection-I and -II at 12 hpi, while expression was decreased in infection-IV." (PMID 34585958, 2021). "A recent study showed that depression might accelerate gastric cancer development through reactive oxygen species-activated tyrosine-protein kinase (ABL1)." (PMID 38068839, 2023). "Another study reveals that depression correlates with worse clinical outcome in gastric cancer patients, and the in vivo and in vitro experiments disclose that gastric cancer–related depression involves the participation of reactive oxygen species via the ABL1-modulated inflammatory pathway." (PMID 33411223, 2021).
lung adenocarcinoma (9 papers, 2015 to 2025). A carcinoma that arises from the lung and is characterized by the presence of malignant glandular epithelial cells. "Lastly, cancer genomic studies indicate that 1–2% of patients with lung adenocarcinoma will have mutations in ABL1." (PMID 26758680, 2016). "Examples include BCR::ABL1 in LAMA84, a blast phase chronic myeloid leukaemia (CML-BP) cell line and EML4::ALK in NCI-H2228 (also known as H2228), a lung adenocarcinoma cell line." (PMID 41421967, 2025). "Data from The Cancer Genome Atlas (TCGA) showed alterations of ABL1 and ABL2 in human lung adenocarcinomas, including copy number enhancement of ABL2 and somatic mutations in ABL1 in 1-2% of patients." (PMID 30956771, 2019).
Pleural effusion (9 papers, 2009 to 2025). The presence of an excessive amount of fluid in the pleural cavity. "At 12 months, the patient achieved complete cytogenetic response (CCyR), but BCR::ABL1 levels remained suboptimal, with recurrent pleural effusion." (PMID 40166069, 2025). "After 6 months, the patient achieved partial cytogenetic response (PCyR) with BCR::ABL1 < 10%, but grade 3 pleural effusion developed." (PMID 40166069, 2025).
chronic lymphocytic leukemia (8 papers, 2014 to 2025). "Moreover, in chronic lymphocytic leukaemia (CLL) the pro-survival protein ABL1 co-localises with F-actin structures to promote amoeboid migration." (PMID 36699013, 2022).
lymphoid leukemia (8 papers, 2014 to 2025). A malignant lymphocytic neoplasm of B-cell or T-cell lineage involving primarily the bone marrow and the peripheral blood. "In the present study, we introduced the T315M mutation into the intrinsic BCR::ABL1 gene of two Ph + myeloid and one Ph + lymphoid leukemia cell lines using the CRISPR/Cas9 system to directly verify the utility of the combined asciminib and ponatinib in human models." (PMID 40208408, 2025).
lymphoid neoplasm (8 papers, 2022 to 2026). A neoplasm composed of a lymphocytic cell population which is usually malignant (clonal) by molecular genetic and/or immunophenotypic analysis. "The diagnosis was Myeloid/Lymphoid neoplasm with ETV6::ABL1 fusion, and the patient received imatinib mesylate treatment." (PMID 38203288, 2023). "To enhance understanding of myeloid/lymphoid neoplasms with ETV6::ABL1 fusion, we retrospectively analyzed the clinical data of a patient with myeloid lymphoid neoplasms with ETV6::ABL1 fusion." (PMID 40887424, 2025).
sarcoma (8 papers, 2014 to 2025). A usually aggressive malignant neoplasm of the soft tissue or bone. "Additionally, positive pan-Trk (clone EPR17341) expression was detected in one intimal sarcoma harboring a ZBTB16::ABL1-fusion." (PMID 40232379, 2025). "As expected, lung tumors with driver fusions harbored mostly EML4/ALK fusions, sarcomas were driven mostly by EWSR1-related and PAX3/FOXO1 fusions, while hematologic malignancies with a spectrum of BCR/ABL1, KMT2A-related, and IGH/MYC fusions." (PMID 33889297, 2021). "One clear cell sarcoma presented with a weak membranous expression and nuclear expression was seen in one MPNST (weak, score 1) as well as one intimal sarcoma with a strong expression harboring a ZBTB16::ABL1 fusion." (PMID 40232379, 2025).
T-cell acute lymphoblastic leukemia (8 papers, 2008 to 2024). Acute lymphoblastic leukemia of T-cell origin. "Of note, other ABL1 fusions that are expressed in Ph-like- and T-cell acute lymphoblastic leukaemias were described to respond to ATP-competitive BCR::ABL1 inhibitors in cells lines and in clinical trials." (PMID 38879610, 2024). "Furthermore, in certain patients with T-cell acute lymphoblastic leukemia (TALL), the gene encoding the nonreceptor protein kinase (c-ABL1) is fused to the EML1 gene on chromosome 14, which causes expression of an EML1-ABL1 fusion protein, that functions as a dysregulated tyrosine kinase." (PMID 19014691, 2008).
Thrombocytopenia (8 papers, 2013 to 2025). A reduction in the number of circulating thrombocytes. "The relapsed cohort exhibited distinct clinical characteristics compared to the sustained remission group, including higher proportions of intermediate- or high-risk stratification, thrombocytopenia at diagnosis, and BCR::ABL1(+)." (PMID 41488897, 2025). "Our retrospective analysis identifies thrombocytopenia at diagnosis, BCR::ABL1(+), and suboptimal early treatment response [persistent minimal residual disease (MRD)] as independent predictors of relapse." (PMID 41488897, 2025). "Independent predictors included thrombocytopenia at diagnosis (OR = 2.09, P = 0.037), BCR::ABL1(+) (OR = 3.85, P = 0.024), and positive MRD on day 19 (OR = 2.09) and day 46 (OR = 5.73, P < 0.001) of induction therapy." (PMID 41488897, 2025). "In conclusion, this study characterizes relapse patterns and prognostic determinants in pediatric ALL, highlighting the interplay among baseline thrombocytopenia, BCR::ABL1 (+) fusion gene, and MRD level." (PMID 41488897, 2025). "Thrombocytopenia at diagnosis, BCR::ABL1(+), and persistent MRD are critical relapse predictors." (PMID 41488897, 2025).
chronic leukemia (6 papers, 2018 to 2023). A slowly progressing leukemia characterized by a clonal (malignant) proliferation of maturing and mature myeloid cells or mature lymphocytes. "Constitutively activated oncogenic mutants of the ABL1 resulting from chromosomal translocations (BCR-ABL1, TEL-ABL1) or episomal amplification (NUP214-ABL1) induce acute and chronic leukemias." (PMID 36959186, 2023).
glioma (6 papers, 2005 to 2024). A benign or malignant brain and spinal cord tumor that arises from glial cells (astrocytes, oligodendrocytes, ependymal cells). "In the subnetworks, several kinases, such as ABL1, ACVR1, EPHA4, MAPK9, PAK1 and SRC, were commonly associated with glioma, cell migration and cell death/survival." (PMID 32392905, 2020).
gastritis (5 papers, 2012 to 2023). Inflammation of the stomach. "In this model, miR-203 was highly expressed in normal marginal zone B-cells, modestly expressed in gastritis tissue and under-expressed in gastric MALT lymphoma tissue with corresponding upregulation of its target ABL1 proto-oncogene." (PMID 23162567, 2012). "Furthermore, MIR203A promoter was hypermethylated, and its target protein, ABL1, was overexpressed in MALT GL in comparison with gastritis, indicating ABL inhibitors as a novel therapeutic approach in MALT GL." (PMID 33806113, 2021).
medulloblastoma (5 papers, 2017 to 2025). A malignant, invasive embryonal neoplasm arising from the cerebellum. "ABL2 amplification has been reported in primary solid and hematologic tumors and in medulloblastoma, the expression of ABL1 and ABL2 has been associated with shorter survival rates." (PMID 40332023, 2025). "To further gain insight into the function of PHF5A in medulloblastoma, we first verified that downregulation of ABL1 reduced pY36-PHF5A level in centrosome, and pY36-PHF5A decreased the protein level of CEP250 in Daoy cells." (PMID 36759599, 2023). "The treatment of inhibitors of both TrkA and ABL1 could inhibit the migration of medulloblastoma cells." (PMID 36759599, 2023). "The database showed that ABL1 is overexpressed in large-scale medulloblastoma (Oncomine)." (PMID 36759599, 2023).
osteosarcoma (5 papers, 2016 to 2024). A usually aggressive malignant bone-forming mesenchymal neoplasm, predominantly affecting adolescents and young adults. "Because PROMPTs are transcribed by Y1P RNA Pol II, which is dependent on elevated levels of ABL1 kinase upon DDR, we also checked for ABL1 expression across cancer types to ascertain whether our proposed mechanism is a unique feature of osteosarcoma cells (bone cancer)." (PMID 38467418, 2024).
thyroid cancer (5 papers, 2015 to 2024). "These included ABL1 and the master regulator NKX2-1 in thyroid cancer, ERBB3 in liver cancer and AKT3 in colorectal adenocarcinoma." (PMID 35725412, 2022).
Arterial thrombosis (4 papers, 2018 to 2025). The formation of a blood clot inside an artery. "However, there is little evidence that proper management of lipid metabolism in patients receiving BCR::ABL1 TKIs will stop arterial thrombosis and prevent vascular occlusive events." (PMID 41473461, 2025).
cervical cancer (4 papers, 2017 to 2024). A primary or metastatic malignant neoplasm involving the cervix. "Specifically, the genes ABL1, BAX, FASN, and PLAU exhibited abnormally high expression levels in cervical cancer specimens, in stark contrast to BCL2, IGF1, and NTRK3, which were markedly under-expressed." (PMID 38988712, 2024).
COVID-19 (4 papers, 2021 to 2024). A disease caused by infection with severe acute respiratory syndrome coronavirus 2. "Tyrosine kinase Abl1 (ABL1) can also regulate the fusion and release of coronavirus spike proteins, with several COVID-19 studies mentioning its potential therapeutic effects." (PMID 39130417, 2024). "Several kinases, such as NTRK1 (10,495th → 29th), FYN (3902nd → 46th), ABL1 (7261st → 91st), and SRC (8965th → 56th), are being studied for repurposing several kinase inhibitors for COVID-19 treatment." (PMID 36291657, 2022).
rhabdomyosarcoma (4 papers, 2019 to 2025). A rare aggressive malignant mesenchymal neoplasm arising from skeletal muscle. "The BCR::ABL1-positive CML cell line KCL-22 and the rhabdomyosarcoma cell line HTB-153 express SLC22A5 mRNA at comparable levels." (PMID 39182842, 2024).